OSR1 (odd-skipped related transcription factor 1)
Diseases named in the same sentence as OSR1 in open-access papers (continued):
Sharing a sentence is not in itself a finding about the gene and the disease.
gastric cancer (6 papers, 2016 to 2024). A primary or metastatic malignant neoplasm involving the stomach. "Like OSR1, TES (testin LIM domain protein) functions as a Mena-dependent tumour suppressor gene in many cancers, including gastric cancer, with loss of expression associated with cancer progression." (PMID 38694815, 2024). "Epigenetic regulation controls OSR1 expression in gastric cancer and lung cacinoma, and mechanically OSR1 is downregulated due to promoter CpG methylation." (PMID 37642735, 2023). "The methylation of the OSR1 promoter leads to the downregulation of OSR1 gene expression in gastric cancer, and OSR1 methylation level is an independent prognostic marker for gastric cancer patients." (PMID 37642735, 2023). "Osr1 has recently been reported as a novel tumor suppressor gene, as well as a potential prognostic biomarker in gastric cancer." (PMID 33005011, 2021). "Previous study of OSR1 in gastric cancer suggested that OSR1 is a functional tumor suppressor in gastric cancer." (PMID 28404905, 2017). "Osr1 has been previously reported as a tumor repressor gene in gastric cancer." (PMID 33005011, 2021). "Previous study showed that OSR1 is a functional tumor suppressor in gastric cancer." (PMID 28404905, 2017). "Furthermore, OSR1 was shown to be silenced by promoter hypermethylation in 51.8% (n = 164) of gastric cancer patients and was identified as an independent predictor of poor survival." (PMID 27782156, 2016).
hepatocellular carcinoma (5 papers, 2020 to 2025). A malignant tumor that arises from hepatocytes. "The expression of wnk1a and osr1b is upregulated in endothelial cells, and WNK1 and OSR1 are upregulated in hepatoma cells during tumor-induced angiogenesis." (PMID 36292952, 2022). "Knockdown of WNK1 in endothelial cells diminishes hepatoma cell migration, and it can be rescued by OSR1 overexpression." (PMID 36292952, 2022). "Because WNK1 activates OSR1/SPAK, if OSR1 or STK39 are involved in tumor-induced angiogenesis, they are supposed to be upregulated from 2 dpi to 3 dpi, so these results indicate that WNK1 and OSR1 in hepatoma cells are involved in tumor-induced angiogenesis." (PMID 36292952, 2022). "Inhibition of WNK1 or its downstream kinases OSR1 (oxidative stress responsive kinase 1)/SPAK (Ste20-related proline alanine rich kinase) using chemical inhibitors decreased ectopic vessel formation as well as proliferation of xenotransplanted hepatoma cells." (PMID 32131390, 2020). "In addition, OSR1 overexpression in HUVEC cells can rescue the reduction of migrated cells caused by shWNK1, indicating that OSR1 is a downstream effector of endothelial WNK1 promoting hepatoma cell migration." (PMID 36292952, 2022). "Moreover, overexpression of OSR1 can rescue the reduced cell migration caused by shWNK1 knockdown in HUVEC cells, indicating OSR1 is downstream of WNK1 in endothelial cells promoting hepatoma cell migration." (PMID 36292952, 2022). "Although this study failed to induce hepatocellular carcinoma due to short-term treatment, the correlation of Osr1 expression levels with cell proliferation and survival, in concurrence with the HFD and DEN treatment, was still worth investigating." (PMID 33005011, 2021).
Hypokalemia (5 papers, 2013 to 2025). An abnormally decreased potassium concentration in the blood. "Because the effect of KS-WNK1 on WNK-SPAK/OSR1 signaling likely predominates when hypokalemia-induced WNK bodies are present, we evaluated the effects of KS-WNK1 deletion on WNK-SPAK/OSR1 localization during dietary K+ restriction." (PMID 40493421, 2025). "Through the analysis of WNK4D561A/+ PHAII model mice crossed with Osr1 and Spak knock-in mice, we showed that the pathogenesis of hypokalaemia is also the result of NCC activation by WNK–OSR1/SPAK signalling, but is not caused by a direct effect of mutant WNK4 on ROMK." (PMID 24655003, 2014). "During hypokalemia, the WNKs activate the kinases STE20/SPS1-related proline-alanine-rich protein kinase (SPAK, also known as STK39) and OSR1 (OXSR1), which phosphorylate NCC directly." (PMID 40493421, 2025). "Taken together, these studies suggest that, in humans, WNK bodies are involved in activation of the WNK-SPAK/OSR1 pathway — not just during frank hypokalemia, but also when blood potassium concentrations are in the low-to-normal reference range of 3.5–4.0 mmol/L." (PMID 40493421, 2025).
Stroke (5 papers, 2021 to 2025). Sudden impairment of blood flow to a part of the brain due to occlusion or rupture of an artery to the brain. "Modulation of NKCC1 and KCC3 expressions by their upstream regulator, WNK-SPAK/OSR1 is implicated in the development and progression of stroke." (PMID 33513812, 2021). "There is a growing body of evidence that the WNK-SPAK/OSR1-CCC pathway is involved in pathogenesis of stroke." (PMID 33513812, 2021). "Lastly, current pharmacological treatments for stroke with respect to potent inhibitors of WNK-SPAK/OSR1 pathway and NKCC1 cotransporter, and activators of KCC3 transporter will be discussed in this review." (PMID 33513812, 2021). "Then, the regulatory role of the with-no-lysine kinase (WNKs) family and STE20/SPS1-related proline/alanine rich kinase (SPAK) or oxidative stress response kinase (OSR1) (WNK-SPAK/OSR1) signaling pathway in stroke will be considered." (PMID 33513812, 2021). "Cerebral edema was shown to be associated with increased phosphorylation of the SPAK/OSR1 kinases playing a key role in NKCC1 activation in various neural cell types and a SPAK kinase inhibitor, ZT-1a, attenuated cerebral edema after stroke." (PMID 35085235, 2022). "Interestingly, we found that the top 3 molecular targets of miR-451a (OSR1, CUX2, PSMB8) have been previously associated with stroke or studied in relation with brain damage." (PMID 35328807, 2022). "Hence, this review summarizes the current understanding of functional regulations of the CCCs implicated in stroke with particular focus on NKCC1, KCC3, and WNK-SPAK/OSR1 signaling and discusses the current and potential pharmacological treatments for stroke." (PMID 33513812, 2021). "Several reports owing to WNK-SPAK/OSR1 kinases as the most involved signaling pathway in the regulation of neuronal Cl− and cell volume homeostasis do exist and these established roles of the WNK-SPAK/OSR1-CCC pathway have alluded to their connection with stroke." (PMID 33513812, 2021). "As the WNK-SPAK/OSR1 pathway reciprocally regulates NKCC and KCC, a growing body of evidence implicates over-activation and altered expression of NKCC1 in stroke pathology whilst stimulation of KCC3 during and even after a stroke event is neuroprotective." (PMID 33513812, 2021). "In fact, the established role of WNK-SPAK/OSR1 signaling pathway in stimulating NKCC1 and inhibiting KCC3, which contribute to the pathogenesis of stroke, are the reasons for our recent pharmacological studies." (PMID 33513812, 2021). "There are several demonstrations that phosphorylation of NKCC1 and KCC3 via the WNK-SPAK/OSR1 signaling may lead to activation of NKCC1 and inhibition of KCC3 either during or post-stroke episode." (PMID 33513812, 2021).
ischemic stroke (4 papers, 2021 to 2025). A stroke disorder caused by obstruction of blood flow to the brain, due to thrombotic (local blood clot formation) or embolic (due to a blood clot or other material traveling from another site) event. "Certainly, the upstream WNK3-SPAK/OSR1 pathway regulation of NKCC1 activity coupled with inhibition of KCC3 is implicated in the pathology of ischemic stroke." (PMID 33513812, 2021). "WNK3-SPAK/OSR1 cation-chloride cotransporter pathway has been reported as a potential therapeutic target in ischemic stroke as knocking down SPAK/OSR1 improved neuroprotection." (PMID 35328807, 2022). "After an ischemic stroke, both NKCC1 and KCCs are phosphorylated via the WNK-SPAK/OSR1 signaling pathway, leading to activation and inhibition of NKCC1 and KCCs, respectively." (PMID 33513812, 2021). "Following ischemic stroke, both NKCC1 and KCCs are phosphorylated via the WNK-SPAK/OSR1 signaling pathway, leading to NKCC1 activation and KCC inhibition." (PMID 33513812, 2021).
prostate carcinoma (4 papers, 2013 to 2024). A carcinoma that arises from epithelial cells of the prostate gland. "In this study, we also castrated PtenloxP/loxP:Osr1-Cre mice at 12- to 16-months of age when prostatic carcinoma/adenocarcinoma develops." (PMID 23308230, 2013). "Using immunohistochemical approaches, we further analyzed tumor cells in PIN and prostatic carcinoma/adenocarcinoma lesions of PtenloxP/loxP:Osr1-Cre mice." (PMID 23308230, 2013). "We only observed malignant prostatic tumors in PtenloxP/loxP:Osr1-Cre mice between 12–16 months of age." (PMID 23308230, 2013). "In 5 of 8 of these older mice, we also observed limited malignant progression of focal areas of high grade PIN lesions to prostatic carcinomas or adenocarcinomas, which is significantly higher than PtenloxP/+:Osr1-Cre and wild type littermates (Fig. 6A1 to 6D3)." (PMID 23308230, 2013). "We also provide evidence that the mammalian homologs of Hyd (UBR5), Lin (LINS1), and Bowl (OSR1/2) constitute an analogous protein degradation pathway in human cells, and that OSR2 promotes prostate cancer tumorigenesis." (PMID 39137945, 2024). "OSR1 was significantly upregulated in GIST compared with normal gastric tissue and was highly expressed in GIST and prostate cancer compared with other human cancers." (PMID 36076237, 2022). "Deletion of Pten using Osr1-Cre provides another novel and useful model for investigating PTEN as a tumor suppressor in prostate cancer development and progression." (PMID 23308230, 2013). "We also provide evidence that the mammalian homologs of Hyd (UBR5, known to be recurrently dysregulated in various human cancers), Lin (LINS1), and Bowl (OSR1/2) constitute an analogous protein degradation pathway in human cells, and that OSR2 promotes prostate cancer tumorigenesis." (PMID 39137945, 2024). "Conditional expression of human AR transgene in mouse prostatic Osr1-lineage cells results in HGPIN and prostatic adenocarcinomas as mice progressed in age10, recapitulating the oncogenic role of the AR as observed in human prostate cancer." (PMID 35902588, 2022). "However, our PtenloxP/loxP:Osr1-Cre mice display an early onset of high grade PIN at 2-weeks of age, with more malignant prostatic tumors not developing until ages greater than 12-months, and with no signs of metastatic disease." (PMID 23308230, 2013).
pseudohypoaldosteronism type 2 (4 papers, 2013 to 2022). A rare inherited form of hypertension characterized by hyperkalemia, hyperchloremic metabolic acidosis, normal or elevated aldosterone, low renin, and normal renal function. "Excessive activity of the WNK-SPAK/OSR1 cascade is the primary cause of PHAII (pseudohypoaldosteronism type II) hypertension and hyperkalemia syndrome." (PMID 35179207, 2022).
colon cancer (3 papers, 2023 to 2025). "In colon cancer patients, reduced OSR1 expression is notably linked with decreased OS and distant metastasis-free survival." (PMID 37642735, 2023). "In addition, by blocking the PI3K/Akt and MAPK pathways, OSR1 inhibits colon cancer cell proliferation, invasion, and migration." (PMID 37642735, 2023).
epilepsy (3 papers, 2022 to 2025). A brain disorder characterized by episodes of abnormally increased neuronal discharge resulting in transient episodes of sensory or motor neurological dysfunction, or psychic dysfunction. "Furthermore, genetic studies on epileptic patients are needed to discover potential genetic variants in WNK proteins that contribute to overactive WNK-SPAK/OSR1 signaling, in order to determine if this is a genetic risk factor for epilepsy." (PMID 37704745, 2024). "Future research should focus on investigating the changes in WNK expression patterns in brain tissue of epileptic patients to gain a more direct understanding of the role of WNK-SPAK/OSR1 pathway in human epilepsy." (PMID 37704745, 2024).
Hepatic steatosis (3 papers, 2021 to 2025). Steatosis is a term used to denote lipid accumulation within hepatocytes. "Using the NAFLD model induced by 60% HFD for 10 weeks, liver pathophysiology focusing on hepatic steatosis and inflammation and their associated signaling pathways are examined in the Osr1 heterozygous and wildtype (WT) mice." (PMID 35657825, 2022). "Furthermore, OSR1 has been implicated in the progression of hepatic steatosis to non-alcoholic fatty liver disease, reinforcing its involvement in metabolic regulation." (PMID 40692711, 2025). "The more severe hepatic steatosis in Osr1 females is confirmed by comparing total area of steatosis with the WT female (p<0.01)." (PMID 35657825, 2022). "This study is aimed to investigate the novel role of Osr1 in promoting the progression of hepatic steatosis to NASH." (PMID 33005011, 2021). "In this study, the Osr1+/− mice displayed more advanced fatty liver disease, featured with more severe steatosis and hepatocellular ballooning, as well as increased macrophage infiltration." (PMID 33005011, 2021). "Worsened hepatic steatosis is a major pathological change in the Osr1+/- liver." (PMID 35657825, 2022). "However, knocking down Osr1 similarly caused more severe hepatic steatosis than WT mice regardless of male or female sex." (PMID 35657825, 2022). "The Osr1+/− mice displayed more severe liver injury, likely a borderline NASH, evidenced by obvious hepatic steatosis, a moderate number of foci, hepatocellular ballooning, and the presence of visible glycogenated nuclei." (PMID 33005011, 2021). "Knocking down Osr1 in mice with HFD-induced obesogenic conditions led to advanced hepatic steatosis compared to WT mice, independent of sex." (PMID 35657825, 2022). "The Odd-skipped related 1 (Osr1) gene was previously reported to play a critical role in embryonic development and as a cancer repressor gene, however its role in overnutrition induced fatty liver disease has never been explored." (PMID 35657825, 2022).
Hydrocephalus (3 papers, 2019 to 2024). Hydrocephalus is an active distension of the ventricular system of the brain resulting from inadequate passage of CSF from its point of production within the cerebral ventricles to its point of absorption into the systemic circulation. "The “cytokine storm” mediated by ChP macrophages and the upregulated phosphorylation of SPAK/OSR1 in choroid plexus epithelial cells constitute critical mechanisms in hydrocephalus." (PMID 38353402, 2024). "SPAK (Ste20-related proline-alanine-rich kinase)/OSR1 (oxidative stress-responsive kinase-1) are essential for regulating NKCC1 protein and are associated with NKCC1 protein activation in the lipopolysaccharides (LPS)-induced hydrocephalus." (PMID 38107410, 2023). "TSOs inhibit CSF hypersecretion by downregulating SPAK and OSR1 in ChP epithelial cells and inhibiting the phenotypic switch of ChP macrophages from M0 to M1 through MAPK signaling pathways, thus preventing hydrocephalus formation." (PMID 38353402, 2024). "Therefore, blocking WNK-SPAK/OSR1 may provide a potent means of synchronously inhibiting of NKCC1-mediated Cl- influx and enhancing KCC-mediated Cl- extrusion for multiple syndromes exhibiting depolarized GABA responses and altered Cl- homeostasis, cerebral edema, or hydrocephalus." (PMID 31165006, 2019).
Infertility (3 papers, 2016 to 2023). "Through a translational approach, we demonstrate that OSR1/Osr1 is a gene important for MD development and endometrial receptivity and is implicated in uterine factor infertility." (PMID 37847567, 2023). "Through this translational approach, we demonstrated that OSR1 in humans and mice is important for MD development and endometrial receptivity and may be implicated in uterine factor infertility." (PMID 37847567, 2023). "The markedly infertile phenotypes of the male DKO mice show that OSR1 and SPAK are potential biomarkers for the diagnosis and assessment of human male infertility." (PMID 27853306, 2016). "Through this translational approach, we demonstrate that OSR1 is a gene important for MD and endometrial development that may contribute to uterine factor infertility in women." (PMID 37847567, 2023).
Lymph node metastasis (3 papers, 2022 to 2024). "Low OSR1 expression (P = 0.025), FIGO stage (P < 0.001), histological differentiation (P = 0.021), and lymph node metastasis (P < 0.001) may affect the OS of OC patients based on Univariate analysis results." (PMID 37642735, 2023).
renal carcinoma (3 papers, 2017 to 2021). A carcinoma arising from the epithelium of the renal parenchyma or the renal pelvis. "In the past three years, a new role of Osr1 as a novel tumor suppressor has been reported in various types of cancer, including lung, gastric and renal carcinoma." (PMID 33005011, 2021). "We examed the role of OSR1 in renal cancer cell invasion by transwell invasion assays." (PMID 28404905, 2017). "The expression profile of OSR1 in RCC indicated that OSR1 might also have tumor suppressor function in renal cancer." (PMID 28404905, 2017).
renal cell carcinoma (3 papers, 2017 to 2023). "Previous research has shown that OSR1 levels were lower in renal cell carcinoma tissues than in normal renal tissues and are negatively associated with histological differentiation grading." (PMID 37642735, 2023). "OSR1 is a tumor suppressor that regulates the proliferation and invasion of renal cell carcinoma cells." (PMID 32650755, 2020).
autism spectrum disorder (2 papers, 2015 to 2022). A spectrum of developmental disorders that includes autism, and Asperger syndrome. "Human Osr1 consists of three exons located on chromosome 2p24, a region recently implicated as a candidate risk susceptibility locus for autism spectrum disorder." (PMID 25822971, 2015).
Hyperkalemia (2 papers, 2013 to 2025). An abnormally increased potassium concentration in the blood. "Since this feature is not present in KS-WNK1–KO mice, our findings suggest that KS-WNK1 recruits an auxiliary mechanism that promotes NCC dephosphorylation during hyperkalemia, independently of WNK4-SPAK/OSR1 signaling." (PMID 40493421, 2025).
Obesity (2 papers, 2020 to 2022). Accumulation of substantial excess body fat. "With respect to cardiometabolic traits, we found that HOXA5 was reported in an EWAS on obesity in African Americans, while OSR1 was reported in an EWAS on insulin resistance and T2D among European populations." (PMID 35836279, 2022).